ST8SIA1 (ST8 alpha-N-acetyl-neuraminide alpha-2,8-sialyltransferase 1)
Diseases named in the same sentence as ST8SIA1 in open-access papers (continued):
Sharing a sentence is not in itself a finding about the gene and the disease.
tumor (continued). "Reduction of GD2 expression by ST8SIA1 knockdown inhibited mammosphere formation and cell motility, and completely blocked tumor formation in vivo, changing the CSC phenotype to a non-CSC phenotype." (PMID 28537895, 2017). "Tumor cells highly expressed donor synthesis genes (NANS, CMAS, and the transporter SLC35A1), while the stroma showed enriched expression of sialyltransferases involved in α2-3, α2-6 and α2-8 sialylation (ST3GAL2, ST3GAL5, ST6GAL2, ST6GALNAC5, ST6GALNAC6, ST8SIA1 and ST8SIA2)." (PMID 38594506, 2024). "In MBM tumors, the expression of ST8SIA1 appears in patches in some specimens, as shown by RNA‐ISH, suggesting that ST8SIA1 expression could be enhanced in the regenerative niche and explaining tumor heterogeneity in MBM." (PMID 32358995, 2020). "The RT-qPCR analysis showed that PLCE1, ST8SIA1, ST3GAL5, and GBA2 were aberrantly regulated between the tumor and nontumor cell lines, while the results of PTGS1 and AMT showed no significance." (PMID 38454278, 2024).
cancer (26 papers, 2013 to 2025). A tumor composed of atypical neoplastic, often pleomorphic cells that invade other tissues. "Understanding the transcriptional regulation of ST8SIA1 is critical to decipher the mechanisms underlying increased GD3S activity in numerous cancers." (PMID 35267607, 2022). "High ST8SIA1 expression has been described in numerous cancers, and is associated with cancer aggressiveness and poor outcome for patients." (PMID 35267607, 2022). "The overexpression of complex gangliosides in cancers is usually correlated with the upregulation of ST8SIA1 gene expression, which encodes the key enzyme for complex ganglioside synthesis, GD3 synthase (CMP-N-acetylneuraminate, GM3 α2,8-sialyltransferase, or ST8Sia I, EC 2.4.99.8, GD3S)." (PMID 35267607, 2022). "ST8SIA1, also known as GD3 synthase (GD3S), is highly expressed in several tumors, and plays an important role in the development and progression of cancer." (PMID 35873547, 2022). "This strategy requires a deep knowledge of the different levels of ST8SIA1 expression and the networks of the genes that are co-regulated in cancers." (PMID 35267607, 2022). "Long non-coding RNA (lncRNA) can also regulate ST8SIA1 expression and cancer cell properties." (PMID 35267607, 2022). "The mRNA and protein levels of ST8SIA1 in cancer tissues and cells are also upregulated." (PMID 35873547, 2022). "ST8SIA1 is responsible for GD3 synthesis from GM3, contributing to the invasive behavior of cancer cells." (PMID 39905449, 2025). "A panel of five DNA methylation markers (FER1L4, ZNF671, ST8SIA1, TBX15, and ARHGEF4) detected 74% of EC cancer patients with an overall specificity of 91%." (PMID 35242243, 2022). "In the CCLE database, expression of JUP, ITGB4, ST8SIA5, ST8SIA1, ST3GAL2, ST3GAL5 and B4GALNT1 in pan-cancer were explored." (PMID 34402716, 2021). "These genes include LRAT, MEIS1, ST8SIA1 and STC2 which have all previously been shown to be subject to transcriptional downregulation as an effect of DNA hypermethylation in human cancers." (PMID 28931069, 2017).
ST8SIA1 also shares sentences with these, for which no sentence is quoted: Alzheimer disease (3 papers); multiple sclerosis (2); astrocytoma (1); chronic myelogenous leukemia (1); Cognitive impairment (1); cutaneous melanoma (1); diabetic cardiomyopathies (1); hyperhomocysteinemia (1); infection (1); intrahepatic cholangiocarcinoma (1); invasive ductal breast carcinoma (1); lung disease (1); Macrocephaly (1); metastatic melanoma (1); pancreatic cancer (1); pituitary adenomas (1); primary immunodeficiency (1); rhabdomyosarcoma (1); schizophrenia (1); small cell lung carcinoma (1).